MLLT11 (MLLT11 transcription factor 7 cofactor)
Description:
Cofactor for the transcription factor TCF7. Involved in regulation of lymphoid development by driving multipotent hematopoietic progenitor cells towards a T cell fate.
Synonyms: AF1Q
Tractability: PROTAC: UniProt records ubiquitination sites on it; ubiquitination databases record sites on it.
Gene: Protein-coding gene on chromosome 1 (151,057,871 to 151,069,544, forward strand). Ensembl gene ENSG00000213190.
Subcellular location: Nucleus; Cytoplasm; Cytoplasm, cytoskeleton, microtubule organizing center, centrosome
Subcellular location (Human Protein Atlas): Cytosol; Nucleoplasm
Gene Ontology:
Molecular function: protein binding
Biological process: extrinsic apoptotic signaling pathway; intrinsic apoptotic signaling pathway; positive regulation of apoptotic process; positive regulation of DNA-templated transcription; positive regulation of mitochondrial depolarization; positive regulation of release of cytochrome c from mitochondria; apoptotic signaling pathway
Cellular component: cytosol; mitochondrion; nucleoplasm; centrosome; cytoplasm; nucleus
Genetic constraint (gnomAD): Loss-of-function variants: 1 observed, 5.67 expected, observed/expected ratio (o/e) 0.18, 90% interval 0.062 to 0.84. That is too few expected variants to judge how well the gene tolerates losing a copy. Missense variants: 87 observed, 113.14 expected, observed/expected ratio (o/e) 0.77, 90% interval 0.65 to 0.92. Synonymous variants: 38 observed, 44.38 expected, observed/expected ratio (o/e) 0.86, 90% interval 0.66 to 1.12.
Homologues: Orthologues: pig MLLT11 (92% identical), dog MLLT11 (89% identical), guinea pig MLLT11 (89% identical), mouse Mllt11 (87% identical), rabbit MLLT11 (87% identical), rat Mllt11 (82% identical), tropical clawed frog mllt11 (51% identical), zebrafish mllt11 (46% identical).
Diseases named in the same sentence as MLLT11 in open-access papers:
MLLT11 is named in the same sentence as 36 diseases in open-access papers, as found by Europe PMC text mining. Sharing a sentence is not in itself a finding about the gene and the disease. The quoted sentences say what the papers report.
breast carcinoma (12 papers, 2013 to 2023). "In this study, MLLT11 was predicted as the gene associated with the metastasis and recurrence of breast cancer." (PMID 38075552, 2023). "A positive association between the levels of expression of MLLT11 and CD44, an adhesion molecule and direct target of the WNT/beta-catenin signaling, has been reported in breast cancer." (PMID 38203610, 2023). "Most importantly, siRNA-based therapy aiming at the knockdown of MLLT11 seems to be a promising approach in breast cancer treatment." (PMID 38075552, 2023). "The expression level of MLLT11 in normal breast epithelial cells MCF10A and MDA-MB-231 was detected, and the results showed that the expression level of MLLT11 in breast cancer epithelial cells was markedly higher than that in normal breast epithelial cells." (PMID 38075552, 2023). "Among the predicted genes, the transcription factor 7 cofactor (MLLT11) was selected as a potential target gene for breast cancer therapy." (PMID 38075552, 2023). "MLLT11 activates the Wnt/β-catenin signaling pathway to promote cell proliferation and the Notch signaling pathway to promote cell apoptosis in breast cancer cells." (PMID 38075552, 2023). "Detection of the MLLT11 expression level not only contributes to the prognosis of breast cancer patients but also serves as an important basis for subsequent treatment." (PMID 38075552, 2023). "The increased expression of MLLT11 in breast cancer patients allows timely prediction of treatment response." (PMID 38075552, 2023). "Collectively, MLLT11 siRNA elicited ameliorative properties on breast cancer cells, possibly via the inhibition of the PI3K/AKT signaling pathway." (PMID 38075552, 2023). "However, there are a limited number of studies on the role of MLLT11 in the metastasis of MDA-MB-231 breast cancer cells." (PMID 38075552, 2023). "In summary, the results of the current study showed that MLLT11 may play an important role in the migration of MDA-MB-231 breast cancer cells and its knockdown may promote apoptosis." (PMID 38075552, 2023). "After MLLT11 knockdown, the invasion ability of MDA-MB-231 breast cancer cells was lowered which might be associated with the decreased levels of MMP2 and MMP9 proteins." (PMID 38075552, 2023). "The results obtained from experiments conducted on cell lines also suggest that MLLT11 may have a positive correlation with the size of mammary tumors in mice." (PMID 38075552, 2023). "Thus, an siRNA specifically targeting MLLT11 was synthesized and experimentally validated in MDA-MB-231 breast cancer cells." (PMID 38075552, 2023).
leukemia (10 papers, 2013 to 2024). A malignant (clonal) hematologic disorder, involving hematopoietic stem cells and characterized by the presence of primitive or atypical myeloid or lymphoid cells in the bone marrow and the blood. "Similarly, expression of MLLT3 and MLLT11 genes that are well studied in leukemia are also found to be strongly associated with the survival of CCA patients." (PMID 33193605, 2020). "MLLT11 is involved in lymphoid regulation and is a known partner gene in rare leukemia translocations." (PMID 32029838, 2020). "MLLT11, as an MLL fusion partner, has shown poor survival benefits in leukemias." (PMID 30285885, 2018).
acute myeloid leukemia (6 papers, 2017 to 2023). Acute myeloid leukemia (AML) is a group of neoplasms arising from precursor cells committed to the myeloid cell-line differentiation. "AF1Q, or MLLT11 (myeloid/lymphoid or mixed-lineage leukemia translocated to 1q), is a mixed-lineage leukemia gene fusion partner, identified as a poor prognostic biomarker in pediatric acute myeloid leukemia (AML) and myelodysplastic syndrome (MDS)." (PMID 31623164, 2019).
ovarian carcinoma (5 papers, 2012 to 2023). A malignant neoplasm originating from the surface ovarian epithelium. "In ovarian cancer cells, the overexpression of MLLT11 was also associated with an activation of WNT/beta-catenin/S100A4 oncogenic signals, resulting in malignant tumor progression and metastasis formation and reduced sensitivity to cancer therapy." (PMID 38203610, 2023). "However, whether the levels of MLLT11 expression could correlate with transformation of the lesion from benign (low MLLT11) to a malignant (high MLLT11) phenotype, particularly in endometriosis-associated ovarian cancer, needs further investigation." (PMID 38203610, 2023). "Mixed-lineage leukemia translocated to 11 (MLLT11), also called the ALL1-fused gene from the chromosome 1q (AF1Q) gene, has been found to be overexpressed in ovarian cancer and to be associated with a poor patient outcome." (PMID 38203610, 2023). "It has been shown that MLLT11 overexpression increases the sensitivity of human squamous cell carcinoma A431 parent (AP) cells and ovarian cancer cell lines to apoptotic drug stimulation." (PMID 38203610, 2023). "Involvement of MLLT11 promoted the progression of ovarian cancer, bladder cancer and endometrial cancer in previous study." (PMID 36686485, 2022). "On the other hand, MLLT11 has also been identified as mediator of basal and 4-HPR-induced apoptosis in ovarian cancer cells, illustrating the somewhat contradictory dual proapoptotic and protumorigenic behavior of the gene in ovarian cancer cells." (PMID 38203610, 2023).
myelodysplastic syndrome (4 papers, 2017 to 2023). A clonal hematopoietic disorder characterized by dysplasia and ineffective hematopoiesis in one or more of the hematopoietic cell lines. "Importantly, report exhibited that MLLT11 is a unfavorable prognostic biomarker for AML, adult normal cytogenetics AML, and adult myelodysplastic syndrome." (PMID 36479666, 2023).
bladder cancer (3 papers, 2022 to 2023). "MLLT11 acted as an oncogene in multiple cancers, for example osteosarcoma, bladder cancer, and lung cancer." (PMID 36479666, 2023). "High levels of MLLT11 were previously associated with low levels of p21 expression and increased proliferation in bladder cancer cells, where the levels of MLLT11 have been shown to be epigenetically regulated by miR-411." (PMID 38203610, 2023). "This indicates that a mechanism for the epigenetic regulation of MLLT11 and p21 expression, similar to those in bladder cancer, may exist in endometriosis." (PMID 38203610, 2023).
squamous carcinoma (3 papers, 2012 to 2023). "In the context of hepatocellular, ovarian and squamous carcinoma and in promyelocytic leukemia cells, MLLT11 was shown to exert proapoptotic functions." (PMID 38203610, 2023).
glioma (2 papers, 2022 to 2023). A benign or malignant brain and spinal cord tumor that arises from glial cells (astrocytes, oligodendrocytes, ependymal cells). "Correlation analyses suggest that declined MLLT11 expression is associated with increased macrophage infiltration in glioma, especially M2 macrophage, and verified by RT­PCR, Western blotting, and immunohistochemistry using our clinical glioma samples." (PMID 36033495, 2022). "In a pathogenic context, MLLT11 has been reported to play an oncogenic role in the development and progression of a variety of human cancers and to act as a tumor suppressor in glioma neural carcinomas." (PMID 38203610, 2023). "MLLT11 plays a crucial role in the progression of glioma and has the potential to be a new prognostic marker for glioma." (PMID 36033495, 2022). "We found that MLLT11 expression is decreased in high-grade glioma tissues; we further verified this result by RT­PCR, Western blotting, and immunohistochemistry using our clinical samples." (PMID 36033495, 2022). "Based on these analyses,MLLT11 may influence the glioma microenvironment via ECM organization and might promote the synapse information to influence the progression of glioma." (PMID 36033495, 2022). "Using large-scale bioinformatic approach and RNA sequencing (RNA-seq) data from public databases The Cancer Genome Atlas (TCGA), Chinese Glioma Genome Atlas (CGGA), and The Gene Expression Omnibus (GEO)), we investigated the relationship between MLLT11 mRNA levels and pathologic characteristics." (PMID 36033495, 2022). "In TCGA datasets, among WHO grade 3 glioma,MLLT11 showed a highly negative correlation with PD-1 (r = -0.34, p = 8.3 × 10-28), PD-L1 (r = -0.41, p = 3.5 × 10-11), TIM3(HAVCR2) (r = -0.4, p = 1.2 × 10-11), and PD‐L2 (PDCD1LG2) (r = -0.58, p < 2.2 × 10-16)." (PMID 36033495, 2022).
amyotrophic lateral sclerosis (1 paper, 2022). Amyotrophic lateral sclerosis (ALS) is a neurodegenerative disease characterized by progressive muscular paralysis reflecting degeneration of motor neurons in the primary motor cortex, corticospinal tracts, brainstem and spinal cord. "Interestingly, the expression of MLLT11 was correlated with several diseases, including amyotrophic lateral sclerosis, coronavirus disease-COVID-19, Huntington’s disease, Parkinson’s disease, and prion disease." (PMID 35558559, 2022).
endometriosis (1 paper, 2023). The growth of functional endometrial tissue in anatomic sites outside the uterine body. "MLLT11 is a gene implicated in cell differentiation and the development and progression of human cancers, but whose role in the pathogenesis of endometriosis is still unknown." (PMID 38203610, 2023). "Therefore, we tested whether reduced MLLT11 expression in endometriosis lesions is associated with increased resistance to apoptotic stimuli." (PMID 38203610, 2023). "Here, we show that reduced cell proliferation in MLLT11 knockdown primary stromal cells from controls resembles the behavior of primary endometriosis stroma cells, which express significantly lower levels of MLLT11 compared to controls." (PMID 38203610, 2023). "As reduced CD44 expression has been reported in the stroma cells of endometriosis lesions, we tested the effects of MLLT11 knockdown on CD44 expression and WNT pathway activity." (PMID 38203610, 2023). "Given the small number of samples of women with Stage I + II endometriosis in our study, we cannot exclude that MLLT11 is also downregulated in these patients." (PMID 38203610, 2023). "Secondly, we conducted an RT-qPCR analysis of MLLT11 expression in primary stroma cells derived from six control endometrial samples and six ectopic lesion samples of women with endometriosis." (PMID 38203610, 2023). "When patients were classified according to their disease stage, a significant reduction in ectopic stromal cell MLLT11 expression was only seen in the advanced rAFS III +IV stages of endometriosis (0.5 median fold change, adjp value = 0.041) (middle)." (PMID 38203610, 2023). "Therefore, in endometriosis stroma cells, the MLLT11 regulates TGFB2 and ACTA2 expression independently, and TGFB2 signaling does not seem to be involved in the regulation of ACTA2." (PMID 38203610, 2023). "We found that the cellular phenotype of MLLT11 knockdown cells resembled the phenotype of the primary endometriosis stroma cells of the lesion, where the levels of MLLT11 are significantly reduced compared to the eutopic stroma cells of women without the disease." (PMID 38203610, 2023). "Our results indicate that MLLT11 may be a new clinically relevant player in the pathogenesis of endometriosis, in particular in the advanced stages of the disease." (PMID 38203610, 2023). "Overall, our results indicate that MLLT11 may be a new clinically relevant player in the pathogenesis of endometriosis." (PMID 38203610, 2023). "The mechanism by which MLLT11 may regulate p21 and p27 protein expression in endometriosis remains unclear, but our data for p27 indicate that regulation occurs at a post-transcriptional level." (PMID 38203610, 2023). "Despite the considerable advances made in understanding the role of MLLT11 in human carcinogenesis and in cortical projection neuron morphogenesis during development, the role of this gene in the pathogenesis of endometriosis remains unclear." (PMID 38203610, 2023). "This indicates that MLLT11 can act as a regulator of endometriosis lesion stroma cell proliferation in vivo and could be an important factor in disease progression." (PMID 38203610, 2023). "However, the discrete mechanisms of MLLT11 and MLLT11-mediated p21 regulation in endometriosis lesions remain to be experimentally tested." (PMID 38203610, 2023). "Overall, our findings are consistent with a model in which a decreased expression of MLLT11 promotes the persistence of endometriosis lesions outside of the uterus by increasing cell adhesion and enhancing the resistance of endometriosis stroma cells to oxidative-stress-mediated apoptosis." (PMID 38203610, 2023). "Therefore, the findings in the present study suggest that reduced MLLT11 expression in endometriosis stroma cells may regulate the profibrotic capacity of these cells and contribute to endometriosis-associated fibrosis." (PMID 38203610, 2023).
endometriosis (continued). "In this study, we found that MLLT11 protein is significantly downregulated in the endometriosis lesion stromal cells of women with Stage III and IV endometriosis." (PMID 38203610, 2023). "We found that MLLT11 is reduced in the ectopic stroma cells of women with advanced stage endometriosis compared to women without endometriosis." (PMID 38203610, 2023). "This showed that MLLT11 expression is downregulated (0.49 median fold change, adjp value = 0.010) in ectopic lesions of women with endometriosis compared to the eutopic endometrium of women without the disease." (PMID 38203610, 2023). "The low levels of expression of MLLT11 in the stroma cells of endometriosis lesions are also consistent with the lack of uncontrolled proliferation of the lesions, ensuring the benign nature of the disease." (PMID 38203610, 2023). "When we stratified the analysis according to the endometriosis disease stage and menstrual cycle phase, we also did not see differences in the levels of glandular epithelial cell MLLT11 expression between the groups (middle and right)." (PMID 38203610, 2023). "Using quantitative RT-PCR and immunohistochemistry, we analyzed 37 women with and 33 women without endometriosis for differences in MLLT11 expression." (PMID 38203610, 2023). "Therefore, in this study, we analyzed the differences in the expression levels of MLLT11 in women with and without endometriosis and evaluated the role of this gene in disease pathogenesis using primary endometrial stroma cells." (PMID 38203610, 2023). "To identify changes that may occur in MLLT11 expression levels in endometriosis, we compared the control endometrium of women without endometriosis to ectopic lesions using qRT-PCR." (PMID 38203610, 2023). "To gain insight into the biological role of reduced MLLT11 expression in endometriosis lesions, we carried out MLLT11 siRNA knockdown experiments in primary endometrial stroma cells (hESCs) derived from the endometrial tissue of four patients without endometriosis." (PMID 38203610, 2023). "However, the role for MLLT11 in the pathogenesis of endometriosis has not been previously reported." (PMID 38203610, 2023).
fragile X-associated tremor/ataxia syndrome (1 paper, 2022). Fragile X-associated tremor/ataxia syndrome (FXTAS) is a rare neurodegenerative disorder characterized by adult-onset progressive intention tremor and gait ataxia. "We also characterized a severe dysplasia of CPNs in Mllt11 cKO mutant neonatal brains; a phenotype found in severe neurodevelopmental disorders such as ASD and Fragile X-associated tremor ataxia syndrome with which Mllt11 dysregulation has been associated." (PMID 35379703, 2022).
non-small cell lung carcinoma (1 paper, 2024). A group of at least three distinct histological types of lung cancer, including non-small cell squamous cell carcinoma, adenocarcinoma, and large cell carcinoma. "LPAR5 stimulates the proliferation and migration potential of non-small-cell lung cancer (NSCLC) by positively regulating MLLT11." (PMID 39671369, 2024).
schizophrenia (1 paper, 2022). A major psychotic disorder characterized by abnormalities in the perception or expression of reality. "The Mllt11 locus has been identified in human genomic regions potentially affected in schizophrenia patients, suggesting a role in CNS development." (PMID 35379703, 2022).
tubulinopathies (1 paper, 2022). "It is presently unclear whether the loss of UL-specific gene expression we observed in our Mllt11 mutants, and tubulinopathies more generally, is primarily because of cytoskeletal dysregulation, or other uncharacterized gene expression pathways functioning downstream of Mllt11." (PMID 35379703, 2022).
varicocele (1 paper, 2024). A condition characterized by the dilated tortuous veins of the spermatic cord with a marked left-sided predominance. "The expression of MEGF9 and MLLT11 increased in the varicocele model group, while the expression decreased after treatment with low, medium, and high doses of BSHXP." (PMID 39391881, 2024). "BSHXP inhibiting MEGF9 and MLLT11 may become a potential therapeutic target for alleviating varicocele and MI." (PMID 39391881, 2024).
Wilms tumor (1 paper, 2023). An embryonal neoplasm characterized by the presence of epithelial, mesenchymal, and blastema components. "Recurrent gains of the 1q21.3 region and upregulation of MLLT11 were reported in the Wilms tumor." (PMID 37245006, 2023).